SLC41A3 (solute carrier family 41 member 3)
Description:
Na(+)/Mg(2+) ion exchanger that acts as a predominant Mg(2+) efflux system at the mitochondrial inner membrane.
Synonyms: FLJ20473; SLC41A1-L2
Tractability: Antibody: its Gene Ontology location is reachable by antibodies, with high confidence; UniProt predicts a signal peptide or a membrane-spanning region; the Human Protein Atlas places it where antibodies can reach. PROTAC: ubiquitination databases record sites on it.
Gene: Protein-coding gene on chromosome 3 (126,005,662 to 126,101,561, reverse strand). Ensembl gene ENSG00000114544.
Subcellular location: Mitochondrion inner membrane
Subcellular location (Human Protein Atlas): Plasma membrane
Gene Ontology:
Molecular function: magnesium:sodium antiporter activity; protein binding; magnesium ion transmembrane transporter activity; monoatomic cation transmembrane transporter activity
Biological process: mitochondrial magnesium ion transmembrane transport; monoatomic cation transport; sodium ion transmembrane transport
Cellular component: mitochondrial inner membrane; plasma membrane
Genetic constraint (gnomAD): Loss-of-function variants: 44 observed, 46.77 expected, observed/expected ratio (o/e) 0.94, 90% interval 0.74 to 1.21. The upper end of that interval is the gene's LOEUF score, 1.21, which puts it in group 5 of 6, group 1 being the genes least tolerant of losing a copy. Missense variants: 550 observed, 615 expected, observed/expected ratio (o/e) 0.89, 90% interval 0.83 to 0.96. Synonymous variants: 256 observed, 259.68 expected, observed/expected ratio (o/e) 0.99, 90% interval 0.89 to 1.09.
Homologues: Orthologues: macaque SLC41A3 (97% identical), chimpanzee SLC41A3 (94% identical), rabbit SLC41A3 (84% identical), guinea pig SLC41A3 (83% identical), pig SLC41A3 (79% identical), rat Slc41a3 (78% identical), mouse Slc41a3 (76% identical), zebrafish slc41a3 (56% identical), tropical clawed frog slc41a3 (54% identical), Caenorhabditis elegans K07H8.2 (41% identical), Caenorhabditis elegans ZK185.2 (36% identical), Drosophila melanogaster CG33181 (35% identical), and 1 more. Paralogues in human: SLC41A1 (50% identical), SLC41A2 (47% identical).
Diseases named in the same sentence as SLC41A3 in open-access papers:
SLC41A3 is named in the same sentence as 25 diseases in open-access papers, as found by Europe PMC text mining. Sharing a sentence is not in itself a finding about the gene and the disease. The quoted sentences say what the papers report.
hepatocellular carcinoma (3 papers, 2024 to 2026). A malignant tumor that arises from hepatocytes. "Conversely, high SLC41A3 expression is closely correlated with poor prognosis in hepatocellular carcinoma patients, leading to a significantly shorter survival period in patients with elevated SLC41A3 expression than in those with normal SLC41A3 expression." (PMID 39200180, 2024). "Recent studies revealed SLC41A3 acted as an oncogene and predicted poor survival for hepatocellular carcinoma (HCC) patients." (PMID 39628683, 2024).
Hypomagnesemia (3 papers, 2016 to 2024). An abnormally decreased magnesium concentration in the blood. "Slc41a3+/+ mice fed a Mg2+-deficient diet for two weeks, displayed hypomagnesemia (serum Mg2+ levels of 0.43 ± 0.04 mM)." (PMID 27349617, 2016). "SLC41A1 hasbeen extensively studied in vitro and in vivo.However, SLC41A1 KO mice have normal serum Mg2+ levels.SLC41A3 on the other hand, is highly expressed in the DCT and invivo knockout models show a hypomagnesemia phenotype." (PMID 38871680, 2024). "Additionally, a mice model deficient in solute carrier family 41 member 3 (Slc41a3) expression, a putative Mg2+ transporter and highly enriched in DCT, was associated with hypomagnesemia without renal Mg2+ wasting." (PMID 33859252, 2021).
Breast invasive carcinoma (1 paper, 2020). "However, decreased SLC41A3 expression was found in the Breast invasive carcinoma (BRCA), kidney chromophobe (KICH), kidney renal clear cell carcinoma (KIRC), uterine corpus endometrial carcinoma (UCEC), and thyroid carcinoma (THCA) compared to their corresponding adjacent non-cancerous tissues." (PMID 33520701, 2020).
hydronephrosis (1 paper, 2016). Collection of urine in the renal pelvis that results in dilatation of the renal pelvis and calyces. "In conclusion, our study of the Slc41a3 mice has identified SLC41A3 as a novel player in Mg2+ (re)absorption and potentially a new factor in the formation of hydronephrosis." (PMID 27349617, 2016). "Importantly, only a subset of the Slc41a3−/− mice developed hydronephrosis, suggesting that Slc41a3−/− mice are more sensitive to the development of hydronephrosis, but that inactivation of Slc41a3 is not causative of hydronephrosis per se." (PMID 27349617, 2016).
viral infection (1 paper, 2022). "SLC-mediated transporters for thyroid hormone, ions, amino acids, choline, and energetic substrates (e.g., SLC16A2, SLC41A3, SLC16A10, SLC44A1, and SLC35C2) were downregulated following viral infection." (PMID 36314791, 2022).
tumor (8 papers, 2020 to 2026). "SLC41A3 is differentially expressed in a variety of tumors and aberrant expression is associated with the progression of the tumor, especially in KIRC and LIHC." (PMID 33520701, 2020). "The results indicated that tumor-stage (P<0.001), tumor-T stage (P<0.001), and SLC41A3 (P<0.001) were associated with overall survival in the TCGA cohort." (PMID 33520701, 2020). "High expression of SLC41A3 was significantly associated with advanced clinicopathological features, poorer patient survival, specific spatial expression patterns, and altered immune cell infiltration in the tumor microenvironment." (PMID 42317344, 2026). "While we have yet to establish a cause-result relationship here, aberrant expression of SLC41A3 could conceivably synergize with MMR deficiency to promote tumor progression." (PMID 33520701, 2020). "This was possibly the major cause of high expression of SLC41A3 in the tumor tissue." (PMID 33520701, 2020). "In terms of DNA methylation, SLC41A3, PPM1G, FAM83D, and UQCRH all showed significantly lower methylation levels in tumor tissues compared with normal tissues, with the most significant decrease observed for SLC41A3." (PMID 41355397, 2025). "In several GEO (GSE36376, GSE22058, GSE64041, GSE76427, GSE63898, GSE14520, GSE54236) and ICGC (ICGC-LIRI) datasets, an increase in SLC41A3 level was found in tumor tissues compared to healthy tissues." (PMID 36844876, 2023). "In the light of the differential expression analysis from the GEPIA database, SLC41A3 was greatly increased in the neoplasm tissues of LIHC than normal tissues." (PMID 34819993, 2021). "Since only SLC41A3 was significantly differentially expressed between LIHC tumor and normal tissues, we further investigated the prognosis of SLC41A3 in LIHC based on the Kaplan-Meier Plotter database." (PMID 34819993, 2021). "The results showed that the expression of SLC41A3 was down-regulated in kidney renal clear cell carcinoma (KIRC), and was associated with poor overall survival and tumor-specific mortality." (PMID 33520701, 2020). "The results demonstrated that the SLC41A3 expression levels were increased with tumor-stage and tumor-grade, but showed opposite results with respect to tumor weight." (PMID 33520701, 2020). "For example, the expression of KIF20A, UCK2, and SLC41A3 should be determined in a larger cohort of HCC cell lines with different phenotypes to demonstrate a putative relationship with tumor aggressiveness." (PMID 32382568, 2020). "After the progression, the molecular testing revealed CCDC6-RET fusion in a liver metastasis, two novel RET fusions (IL6ST-RET and SLC41A3-RET), and an ALK fusion with a mutation allele frequency of 0.19% in circulating tumor DNA (ctDNA), including the known EGFR 19del." (PMID 41907614, 2026). "Compared to healthy tissues, LIHC had a significantly lower DNA methylation level of SLC41A3, which may account mainly for a high-expressed SLC41A3 in tumor tissues." (PMID 36844876, 2023). "Finally, our data confirmed that SLC41A3 expression in neoplasm cells of LIHC was significantly increased by qRT-PCR assay." (PMID 34819993, 2021). "Taking together, these results suggest aberrant SLC41A3 expression may alter tumor immune microenvironment." (PMID 33520701, 2020). "Furthermore, the correlation between SLC41A3 expression and immune cells infiltration, immune checkpoint, mismatch repair (MMR), DNA methyltransferase (DNMT), tumor mutation burden (TMB), and microsatellite instability (MSI) were calculated using data form TCGA database." (PMID 33520701, 2020). "Whereas SLC41A3 expression was downregulated in BRCA, CESC, KICH, KIRC, THCA and UCEC compared with non-tumor tissue." (PMID 33520701, 2020). "The results from three different databases exhibited high SLC41A3 expressions in BLCA, CHOL, COAD, LIHC, LUSC, and READ, but low SLC41A3 expression in BRCA, KICH, KIRC, KICH, THCA, and UCEC compared with non-tumor tissue." (PMID 33520701, 2020).
cancer (4 papers, 2020 to 2022). A tumor composed of atypical neoplastic, often pleomorphic cells that invade other tissues. "Taken together, the expression of SLC41A3 was significantly heightened and exhibited an association with the carcinoma stage in LIHC." (PMID 34819993, 2021). "We analyzed the correlation between TMB or MSI and SLC41A3 expression in 33 common cancers to explore the relationship between the SLC41A3 activity and mutation in pan-cancer." (PMID 33520701, 2020). "In this study, we analyzed the pan cancer expression of SLC41A3 and the association of its aberrant expression with patient performance." (PMID 33520701, 2020). "The Kaplan-Meier analysis was used to evaluate the association between SLC41A3 expression and overall survival in pan-cancer based on the TCGA database." (PMID 33520701, 2020). "Further research is required to fully establish the contribution of each specific gene, including four outstanding genes (Slc41a3, Fabp5, Mthfd1l and Igdcc4) with clinical relevance in human cancer." (PMID 33917315, 2021). "Slc41a3 overexpression has been reported in cancer for nutrient and Mg2+ transport to meet the needs for aberrant metabolism and proliferation." (PMID 33917315, 2021). "In order to investigate the application of SLC41A3 in cancer prognosis, we built a nomogram for predicting the overall survival of LIHC patients in the TCGA cohort." (PMID 33520701, 2020). "This study was designed to analyze the expression status and prognostic significance of SLC41A3 in pan-cancers." (PMID 33520701, 2020). "Although previous results support prognostic implications of SLC41A3 in different cancers, its potential role warranted additional investigations." (PMID 33520701, 2020). "In this study, we examined the expression of SLC41A3 in normal tissues, various cell lines, and pan-cancer." (PMID 33520701, 2020). "Our results demonstrated that the expression of SLC41A3 was altered in various cancers and can affect cancer patient prognosis." (PMID 33520701, 2020). "The Cox regression and Kaplan-Meier analyses were used to evaluate the prognostic value of SLC41A3 in pan-cancer." (PMID 33520701, 2020). "Meanwhile, we also evaluated the prognostic value of SLC41A3 in pan-cancer based on The Cancer Genome Atlas (TCGA) dataset." (PMID 33520701, 2020). "Here, we evaluated the correlation between the immune cell infiltration and SLC41A3 expression in pan-cancer based on the TIMER database." (PMID 33520701, 2020). "Herein, our study is aimed at exploring what function SLC41A3 has in cancers." (PMID 34819993, 2021). "So far, few studies explore the relationship existing between carcinomas and SLC41A3." (PMID 34819993, 2021). "The role of SLC41A3 in cancer prognosis and immune regulation has rarely been reported." (PMID 33520701, 2020). "Aberrant SLC41A3 expression may exert impact on cancer progression, in part, through influence on mechanisms that maintaining genome stability." (PMID 33520701, 2020). "Furthermore, three different databases based on the TCGA cohorts were used to evaluate the mRNA expression of SLC41A3 in thirty-three cancer types." (PMID 33520701, 2020). "The cancer stage and SLC41A3 were included as prognostic factors in the nomogram." (PMID 33520701, 2020). "In addition, we also observed positive correlation between immune checkpoint gene and SLC41A3 expression in pan-cancer." (PMID 33520701, 2020). "Subsequently, we evaluated the mRNA expression of SLC41A3 in twenty-two cancer cell lines from the CCLE database, and the results revealed that the expression levels of SLC41A3 varied significantly among cancer cell lines [Kruskal-Wallis test P<0.001 with ANONA test P<0.001]." (PMID 33520701, 2020). "Mg2+ homeostasis may also influence immune function, such as immune cell adherence and macrophage response, and aberrant expression of SLC41A3 may alter cancer microenvironment and immune response, thus the overall clinical outcome." (PMID 33520701, 2020).
cancer (continued). "The results showed that the high expression SLC41A3 group was significantly enriched with pathways associated with tumorigenesis, including cell-cycle, NOTCH signaling pathway, ADHERENS junction, WNT signaling pathway, pathways in cancer, and TGF beta signaling pathway." (PMID 33520701, 2020). "The results of previous studies have confirmed that SLC41A3, SEC61A1, LRP4, PPM1G, and HSP90AA1 play important roles in cancer progression." (PMID 35799605, 2022). "Therefore, it is possible that SLC41A3 may serve different functions in different types of cancers." (PMID 33520701, 2020). "Therefore, we proposed that SLC41A3 may serve as a potential prognostic biomarker for cancer." (PMID 33520701, 2020). "A significant correlation was found between increased SLC41A3 expression and increased MSI in various cancers, such as CESC, LIHC, and TGCT, while, decreased SLC41A3 expression was inversely correlated with MSI in DLBC and LAML." (PMID 33520701, 2020). "SLC41A3 is a mitochondrial bound Mg2+ channel that participates in maintaining Mg2+ homeostasis, however, its aberrant expression in cancer is not well studied." (PMID 33520701, 2020). "Furthermore, we analyzed the relationship between SLC41A3 expression and disease-specific survival (DSS) in pan-cancer." (PMID 33520701, 2020). "Additionally, correlation analysis suggested a significant correlation between SLC41A3 and TMB, MSI, MMR, DNMT, and immune cells infiltration in various cancers." (PMID 33520701, 2020).
degenerative diseases (1 paper, 2021). "These include Spon2, Adam19, Arntl, Cdkn1a, Cry2, Per2, Per3, Wee1, Rcan1, Slc41a3, Errfi1, and Bhlhe41, which are related to numerous cardiovascular and degenerative diseases of other organs as well as varying aging processes." (PMID 33668521, 2021).
SLC41A3 also shares sentences with these, for which no sentence is quoted: diabetes (2 papers); alcoholism (1); Ataxia (1); Bladder Urothelial Carcinoma (1); cholangiocarcinoma (1); colon adenocarcinoma (1); Esophageal carcinoma (1); head and neck squamous cell carcinoma (1); kidney chromophobe (1); lung adenocarcinoma (1); Lung squamous cell carcinoma (1); Obesity (1); rectum adenocarcinoma (1); stomach adenocarcinoma (1); thyroid carcinoma (1); type 2 diabetes mellitus (1); uterine corpus endometrial carcinoma (1).